CD4 (CD4 molecule)
Diseases named in the same sentence as CD4 in open-access papers (continued):
Sharing a sentence is not in itself a finding about the gene and the disease.
tumor (continued). "In the 95–600 mg tumor group, depletion of CD8+ cells alone or both CD4+ and CD8+ cells diminished the effect of NK cell therapy, whereas depletion of CD4+ cells alone did not affect OS." (PMID 39835538, 2025). "Further analysis of T cells subsets showed that both CD4+ and CD8+ T cells were present in the tumor samples." (PMID 40358156, 2025). "Tregs, a specific subset of CD4+ CD25+ FoxP3+ T lymphocytes, suppress the anti-tumour immune responses and stimulate tumour growth." (PMID 40852716, 2025). "A similar outcome was seen in CD4- and CD8-depleted animals (respectively), suggesting that these immune components are essential for the protective anti-tumor response mediated by either active or inactive OpdA." (PMID 41019059, 2025). "We further characterized non-tumor TIM-3 positive cells with additional broad immune markers (CD3, CD4, CD8 and CD68)." (PMID 39953623, 2025). "We further performed mIF on tumor tissue samples before and after NAIC to detect the dynamic changes of CD4+CXCL13+ cells upon treatment." (PMID 40295492, 2025). "The incorporation of L7/L12 should also be accompanied by assessments of cytokine profiles, as increased secretion of IFN-gamma from CD4+ and CD8+ T cells indicates a favorable Th1-type immune response, which is beneficial for anti-tumor immunity." (PMID 40453095, 2025). "Our study revealed significant enrichment of CXCR5+CD4+ and CXCR5+CD8+ T cell in ES-SCLC patients exhibiting robust immunotherapy responses, suggesting their cooperative roles in shaping anti-tumor immunity." (PMID 40404633, 2025). "CD4+, CD8+ T cells, as well as Th1 and Th17 cells, are well‐recognized as anti‐tumor immune cells, and their degree of infiltration is positively correlated with prognosis." (PMID 39811936, 2025). "With the assistance of DCs and CD4+ T cells, CD8+ T cells exerted a defensive function in TME to suppress tumor progression." (PMID 40777025, 2025). "In the CD3 T cell population, both CD4+ and CD8+ compartments were significantly increased in terms of the absolute number of cells for grams of tumor." (PMID 40611330, 2025). "The tumor antigens within MHC-I and MHC-II molecules are cross-presented to CD8+ T cells and CD4+ T cells, initiating the adaptive immune response." (PMID 40688079, 2025). "Tumor-infiltrating lymphocytes (TILs) comprise diverse populations, including CD8+ T cells, CD4+ T cells, B cells, NK cells, and regulatory T cells (Tregs), all exerting significant impacts on tumor development and progression." (PMID 39858465, 2025). "-Delayed tumor growth.-↑ infiltration of CD8+ and CD4+ T cells into the TME.-↑ activation of dendritic cells.-↓ tumor-infiltrating MDSCs." (PMID 39857682, 2025). "Although increased infiltration of CD3+CD4+ and CD3+CD8+ T cells was seen in both responders' and non-responders' biopsy samples, expression of CD39, a surrogate marker of tumor-reactive CD8+ cells, was elevated only in patients with pathological CR." (PMID 41445946, 2025). "Tumor-infiltrating lymphocytes (TILs) include CD8+ T cells and CD4+ T cells, for example, are unique independent prognostic markers for UVM patients and play essential roles in tumor recurrence, metastasis, dissemination, and responsiveness to immunotherapy." (PMID 40703526, 2025). "Compared to the NQO1 group, the combined Plerixafor group indicated significantly increased infiltration of CD3+ T cells in the tumor tissue, while the infiltration of Treg cells (FOXP3+CD4+ and FOXP3+CD25+CD4+) was significantly reduced." (PMID 41028931, 2025). "Treatment of tasquinimod alone or in combination with cisplatin significantly increased CD4+ and CD8+ T cell infiltration into the tumor compared to vehicle control or cisplatin alone treatment groups." (PMID 41173834, 2025). "The frequency of memory CD4+ T cells was reported to be higher in SCC as was the frequency of regulatory T cells (Tregs), suggesting a more immunosuppressive tumour microenvironment." (PMID 40639721, 2025).
tumor (continued). "This triggered activation of tumor‐specific CD8+ and CD4+ cytotoxic T cells, which migrated to tumor sites, exerted cytotoxic activity, and established durable immunological memory." (PMID 40878391, 2025). "Compared with A41L-intact VVLΔTKΔN1L, the infiltration of CD4+ T and natural killer (NK) cells in TME and the proportion of dendritic cell (DC), activated DC, CD86+ DC and CD8+ T cells in tumor tissues increased." (PMID 40350204, 2025). "The recruitment of CD4+ and CD8+ T cells to tumor sites is likely influenced by this inflammatory milieu and regulated by ITGA4." (PMID 40012546, 2025). "Flow cytometry-based profiling of tumor-infiltrating lymphocytes across cancers confirmed substantial infiltration of both CD8+ and CD4+ T cells in KIRC." (PMID 40821775, 2025). "Conversely, eliminating IL-2 expression using tacrolimus (FK506), an inhibitor of calcineurin, also diminished the difference in tumor growth, as well as the IFN production by WT and Gsdmd–/– lymphocytes, including CD4+ T, CD8+ T, and NK cells." (PMID 40759573, 2025). "In the tumor parenchyma, the proportion of YAP1-positive cells was positively correlated with the proportion of CD4-positive cells and FOXP3-positive cells (r = 0.732, P = 0.004; r = 0.5780, P = 0.03)." (PMID 40051494, 2025). "In the KRAS G12C-mutated CT26 mouse model, MRTX849 reduced myeloid-derived suppressor cells in the tumor, while increasing the infiltration of M1-type macrophages, dendritic cells, and CD4+ and CD8+ T cells, demonstrating a significant tumor-shrinking effect." (PMID 40303413, 2025). "The PD-1 and CTLA-4 receptors inhibit the anti-tumor response of CD4+ and CD8+ T lymphocytes after attachment of PD-L1 and PD-L2, expressed on the surface of tumor cells." (PMID 40574027, 2025). "Clinically, CD4+ T cells contribute to tumor immunity in diverse ways, including direct cytotoxicity against MHC class II-expressing tumor cells, supporting CD8+ T cell responses, and enhancing the efficacy of immune checkpoint blockade therapies." (PMID 40660400, 2025). "Functional reactivity was evidenced by the upregulation of 4-1BB in CD8+ T cells, OX40 in CD4+ T cells, and increased production of IFN-γ and TNF-α upon autologous tumor stimulation." (PMID 40806287, 2025). "By immunohistochemistry, elevations in CD4+ and CD8+ T cells and a decline in programmed cell death protein 1 (PD-1) expression on tumor-infiltrating T cells were observed." (PMID 39971377, 2025). "PD-1 is also expressed on CD4+ T cells, regulatory T cells, B cells, and subsets of NK/NKT cells, where it contributes to broader immunoregulatory effects within the tumor microenvironment." (PMID 41463022, 2025). "We then investigated the anti-tumor immune responses by evaluating the expression levels of CD3+, CD4+, and CD8+ T cells, as well as DC maturation (CD11c+, CD86, and CD80) in tumors." (PMID 40234392, 2025). "First subset of classical DCs (cDC1) is the principal cells for cross-presenting tumor antigens to CD8+ T-lymphocytes and initiating cytotoxic responses, besides priming CD4+ T-cells." (PMID 41410751, 2025). "In mouse melanoma models, cIgG with sialylation can inhibit T cell proliferation by reducing the frequency of CD4+ and CD8+T cells in tumor tissues, thereby promoting tumor growth." (PMID 40535807, 2025). "From the results obtained in vivo, it is also possible to verify that the reduction in PD-L1 levels facilitates the infiltration of CD4+ T cells and CD8+ T cells into tumor, culminating in a reduction in tumor growth." (PMID 40730655, 2025). "The density of CD4+ and CD8+ TILs was evaluated in intratumoral (within tumor cell nests) and stromal (the surrounding stroma of tumor cell nests) areas." (PMID 40444078, 2025). "In certain cases, soluble B7-H3 proteins, have been observed to co-stimulate CD4 and CD8 T cell proliferation and IL-12 production through matrix metalloproteinases (MMPs), thereby facilitating the clearance of tumours." (PMID 40994140, 2025).
tumor (continued). "In this experiment, mice with cotransferred Gsdmd–/– CD4+ T cells and WT CD8+ T cells had an increased tumor burden and reduced T cell function compared with mice receiving both WT T cells." (PMID 40759573, 2025). "Since CD4+ and CD8+ T cells are key in combating tumor cells, a reduced lymphocyte count often signifies an impaired tumor-specific immune response." (PMID 40458729, 2025). "On the other hand, when we consider the tumor burden, a greater proliferation of CD4+ CAR-T cells was observed: Ki67 99.46% of CD4+ CAR-T (range 72.12 – 100) in HTB vs 80.64 (13.61 – 100) in LTB group, p = 0.03." (PMID 41488626, 2025). "The kinetics and extent of the tumor immune infiltrate positive for CD4 and CD8 following ECT were contingent upon both: the chemotherapeutic drug used and the type of tumor." (PMID 40007542, 2025). "It has been well-documented that the infiltration levels of CD4+ and CD8+ T cells are typically elevated in tumor tissues relative to normal tissues." (PMID 41170390, 2025). "T lymphocyte subsets—including CD4+ helper T cells, regulatory T cells (Tregs), and CD8 + cytotoxic T cells—exert distinct immunological functions within the tumor microenvironment (TME)." (PMID 40647419, 2025). "Classical lymphocyte subpopulations include T cells (CD4+ and CD8+), B cells, and natural killer (NK) cells, all of which contribute to controlling tumor growth." (PMID 40958865, 2025). "In PDAC, IL-7 and its activation of the JAK/STAT signaling pathway may make tumor cells resistant to chemotherapeutic agents such as gemcitabine and accelerate tumor progression.Normally, IL-7 binding to its receptor promotes the growth and maturation of CD4+T cells by facilitating pSTAT5-NT." (PMID 39958351, 2025). "Collectively, TNBCvax vaccination effectively elevated pro-inflammatory and cytotoxic activity of CD4+ and CD8+ T cells and enhanced central memory T cell responses, and resulting in stronger anti-tumor immune responses compared to CpG control group." (PMID 40969744, 2025). "Recent studies have demonstrated that thermal ablation therapies, such as cryoablation, can modulate tumor-infiltrating immune cells by increasing CD8+ T cell infiltration and altering the CD4+/CD8+ ratio, potentially enhancing antitumor immunity." (PMID 41179298, 2025). "Flow cytometric analysis revealed that the proportion of PD-1-expressing CD4+ T-cells, which are targets of MDV tumorigenesis, increased in the spleen and tumor tissues of chickens with MD." (PMID 40430752, 2025). "Across both tumor and adjacent tissues, CD8+ T cells consistently exhibited higher expression levels than CD4+ T cells." (PMID 41181122, 2025). "DCs are able to acquire tumor antigens from the TME and activate CD8+ T cells and CD4+ T cells and maintain antitumor immune responses by cross-presentation via MHC-I molecules or direct antigen presentation via MHC-II molecules." (PMID 40385461, 2025). "In 4T1 tumor-bearing mice, the nanocarrier combined with NIR light promoted intratumoral infiltration of CD8+/CD4+ T cells, elevated anti-tumor cytokine levels, and inhibited tumor growth and lung metastasis." (PMID 40860139, 2025). "CD4 expression is dynamically regulated during TEX, particularly in the HCC tumor microenvironment, where TEX cells compromise immune surveillance and therapeutic efficacy." (PMID 41009979, 2025). "CODEX multiplexed IF showed that Takinib-treated tumors had increased total and proliferating CD4+ and CD8+ T cells, as well as granzyme B-expressing CD8+ T cells that were physically closer to tumor cells." (PMID 41280086, 2025). "The significant correlations observed between these genes and various immune cell types, including CD4 + T cells, B cells, macrophages, and CD8 + T cells, emphasize the immunomodulatory roles of these genes in shaping the tumor microenvironment." (PMID 40817072, 2025).
tumor (continued). "By designing DCs to present tumor antigens on syngeneic MHC class I and provide allo-CD4+ T cell help through mismatched MHC class II, we achieved potent coordination between CTLs and helper T cells to reinforce antitumor immunity." (PMID 40857404, 2025). "Guided by bioinformatic predictions, we therefore co-cultured tumor cells with CD4+ T cells and measured cytokines in the supernatant, and the results confirmed that FMR1 promotes CD4+ T-cell activation." (PMID 41184982, 2025). "To dissect the cellular immune response against tumors, we assessed the levels of tumor-infiltrating CD8+ and CD4+ T cells post-third immunization." (PMID 40606756, 2025). "It is predominantly expressed in natural killer cells, regulatory T cells, CD4 + T cells, CD8 + T cells, and tumor-infiltrating lymphocytes." (PMID 40417700, 2025). "Recent studies have identified an immune cell triad of CD4+ T cells, CD8+ T cells, and dendritic cells that coalesce to reprogram CD8+ T cells for tumor clearance." (PMID 40314973, 2025). "Analysis of tumor-infiltrating lymphocytes revealed increased IFN-γ production by γδ T cells and CD4+ cells in the presence of inulin compared with anti-PD-1 monotherapy." (PMID 40770084, 2025). "Perhaps the most investigated goal has been a signature describing CD4 and CD8 lymphocytes that recognize tumor-specific neoantigens." (PMID 40773142, 2025). "A similar conclusion comes from a separate study using an engineered high-mutational load murine mammary tumor model, in which B cells, CD4 cells, and CD8 cells contributed to checkpoint blockade mediated tumor control." (PMID 40356924, 2025). "Analysis by multicolor immunofluorescence and immunohistochemistry revealed that rPR8-CCL19 remodeled the tumor TME, characterized by the robust recruitment and activation of both CD4+ and CD8+ T cells." (PMID 41446741, 2025). "Although moDs can activate CD4+ and CD8+ T-cells and cross-present antigens, dendritic cell maturation in tumor tissue is frequently dysregulated, shifting the balance toward immature states." (PMID 41410751, 2025). "For instance, Astragalus polysaccharides stimulate CD4+ and CD8+ T-cells proliferation and cytokine secretion via the JAK/STAT pathway, thereby enhancing T-cells-mediated anti-tumor responses." (PMID 40406101, 2025). "In similar regards, ER-positive BC patients present higher proportion of NK cells and neutrophils than other tumor infiltrating immune cells such as cytotoxic T cells (CD8+T) and memory T cells (CD4+T)." (PMID 40438111, 2025). "A clinical study published in 2010 revealed that patients with head and neck squamous cell carcinoma treated with 1,25(OH)2D3 had significantly increased levels of CD4+ and CD8+ T cells in their tissues and a longer time to tumor recurrence." (PMID 40452814, 2025). "mIF staining revealed significant increases in functional T cells (CD4+ granzyme B+ and CD8+ granzyme B+ T cells) and structural changes in tumor vessels (CD31/aSMA staining) in the SBI-0206965-treated group." (PMID 39744218, 2025). "Further, compared to the oe‐NC+M2pep‐Cs NPs/Plerixafor group, the number of CD4+ T cells and CD8+ T cells was significantly decreased in the tumor tissues of mice in the oe‐CXCR4+M2pep‐Cs NPs/Plerixafor group." (PMID 40536774, 2025). "Originally identified as a co‐receptor for HIV‐1 in CD4+ T cell infection, CXCR4 expression has been detected in numerous cancer cells, often overexpressed at tumour sites alongside elevated stromal tissue CXCL12 levels." (PMID 39779470, 2025). "cDC1s specialize in acquiring antigens from tumor cells and cross-presenting these tumor antigens to prime and activate CD8+ T cells, whereas cDC2s are more adept at supporting CD4+ T cell response." (PMID 41459487, 2025). "Activated DCs migrate into the draining lymph nodes and activate the initial T cells to cross-present tumor antigens from MHC-I and II molecules to CD8+ and CD4+ T cells." (PMID 40486836, 2025).
tumor (continued). "LMP1/2A mice showed significantly higher numbers of activated memory T cells in both CD4+ and CD8+ αβT cell fractions compared to controls, suggesting their role in the elimination of tumor cells." (PMID 40534857, 2025). "These APCs take up antigens released through the process of ablation, including microfragments of the ablated tumour, and migrate to lymph nodes and the spleen in order to present these antigens to CD8+ cytotoxic T-cells and CD4+ helper T-cells." (PMID 40142250, 2025). "Inactivating aberrations in STK11 have been identified as critical drivers of an immunosuppressive tumor microenvironment in NSCLC, characterized by diminished infiltration of CD3+, CD4+, and CD8+ tumor-infiltrating lymphocytes and an accumulation of TANs." (PMID 41254689, 2025). "SM-102-treated groups exhibited higher CD69 levels in CD8+ and CD4+ T cells than PBS and MC3 controls, indicating a preferable status of T cells for tumor killing." (PMID 41041043, 2025). "Regardless of the fractionation scheme, irradiation reduces the proportion of tumor macrophages and myeloid cells while increasing the proportion of CD8+ and CD4+ T cells." (PMID 40406256, 2025). "Specifically, CD8+ T cells recognize tumor antigens presented by MHC I molecules, while CD4+ T cells identify antigens shown by Major Histocompatibility Complex II (MHC II) molecules." (PMID 41019037, 2025). "Immunofluorescence was used to identify CD4+ and CD8+ T cell infiltration in the parenchyma and margins of the tumor tissue." (PMID 40191185, 2025). "Comparing with PB, tumor samples showed slightly higher levels of CD8+ T cells and NK cells, and lower levels of CD4+ T cells, consistent with the established role of CD8+ T cells and NK cells as key effectors in tumor infiltration and cytotoxic activity." (PMID 41221282, 2025). "This strategy reprogrammed the tumor microenvironment, increased CD8+ and CD4+ T cell infiltration, and triggered strong antitumor immunity, significantly reducing tumor growth and lung metastasis without systemic toxicity." (PMID 40563442, 2025). "Next, we studied the spatial relationship between T-cell populations (CD4+ and CD8+ T cells), G9-expressing tumor cells (PanCK+G9 + ), and Tim3 expression on T cells." (PMID 39910335, 2025). "TLR7 inversely correlated with tumor purity, and positively with B cells, CD8+ T cells, CD4+ T cells, macrophages, neutrophils, and dendritic cells." (PMID 39857735, 2025). "High expression of TIM-3+ CD4+ Th1 cells and TIM-3+ CD8+ T cells plays tumour-promoting roles in HPV-positive cervical cancer." (PMID 40038352, 2025). "In HFD‐fed mice, the proportion of CD4+ T cells was greater than that of CD8+ T cells in the TR@siSCD1 group, possibly because TR@siSCD1 alone mainly targets tumor cells and cannot block lipid uptake by T cells." (PMID 39736148, 2025). "This expression is crucial as it enhances the responsiveness of CD4+ and CD8+ T-cells, which are key players in controlling tumor growth." (PMID 40497988, 2025). "Once matured and loaded with antigen, these DCs are reinfused intradermally, subcutaneously, or intravenously, where they migrate to lymph nodes and present tumor‐derived peptides on MHC molecules to naïve CD8+ and CD4+ T cells." (PMID 40667699, 2025). "Imbalance in the Th1/Th2/Th17 subsets differentiated from CD4+CD25− T cells (such as a Th2 bias) disrupt the immunoregulatory network and promotes tumor progression." (PMID 41394858, 2025). "These bacteria also suppress inflammatory cytokines, including mRNA of NF-κB and IL-6 in the tumor microenvironment, and reduce CD4 + and CD206 + T cells in the spleen, contributing to an anti-tumor immune response." (PMID 40924302, 2025). "None of the tested electric pulse protocols affected the distance of CD4+ and CD8+ T cells to the tumor vessels at either time point." (PMID 39967849, 2025).